FRRS1L (ferric chelate reductase 1 like)
Description:
Important modulator of glutamate signaling pathway.
Synonyms: C9orf4; CG-6; CG6; DEE37; EIEE37
Tractability: Antibody: UniProt places it where antibodies can reach, with medium confidence; UniProt predicts a signal peptide or a membrane-spanning region; its Gene Ontology location is reachable by antibodies, with medium confidence. PROTAC: its protein half-life has been measured.
Gene: Protein-coding gene on chromosome 9 (109,130,293 to 109,167,249, reverse strand). Ensembl gene ENSG00000260230.
Subcellular location: Cell membrane; Synapse
Gene Ontology:
Molecular function: dynein intermediate chain binding; protein-containing complex binding
Biological process: regulation of glutamate receptor signaling pathway; regulation of postsynaptic membrane neurotransmitter receptor levels
Cellular component: plasma membrane; synapse; endoplasmic reticulum membrane; postsynapse
Genetic constraint (gnomAD): Loss-of-function variants: 12 observed, 13.76 expected, observed/expected ratio (o/e) 0.87, 90% interval 0.56 to 1.41. The synonymous counts are far from expectation, so gnomAD's model fits this gene poorly and the ratio says little. Missense variants: 277 observed, 243.49 expected, observed/expected ratio (o/e) 1.14, 90% interval 1.03 to 1.26. Synonymous variants: 125 observed, 95.56 expected, observed/expected ratio (o/e) 1.31, 90% interval 1.13 to 1.52.
Gene-disease validity (ClinGen):
ClinGen rates the evidence that FRRS1L causes each of these diseases.
genetic developmental and epileptic encephalopathy (autosomal recessive): Definitive. A complex neurodevelopmental disorder characterized by a range of developmental delays and epileptic encephalopathy phenotypes.
Homologues: Orthologues: chimpanzee FRRS1L (100% identical), macaque FRRS1L (98% identical), dog FRRS1L (96% identical), pig FRRS1L (95% identical), rat Frrs1l (93% identical), mouse Frrs1l (93% identical), rabbit FRRS1L (76% identical), guinea pig FRRS1L (75% identical), zebrafish frrs1l (72% identical), tropical clawed frog znf830 (68% identical), Drosophila melanogaster CG8399 (20% identical), Caenorhabditis elegans C13B4.1 (19% identical), and 6 more. Paralogues in human: FRRS1 (25% identical), REELD1 (12% identical).
Diseases named in the same sentence as FRRS1L in open-access papers:
FRRS1L is named in the same sentence as 21 diseases in open-access papers, as found by Europe PMC text mining. Sharing a sentence is not in itself a finding about the gene and the disease. The quoted sentences say what the papers report.
epilepsy (5 papers, 2017 to 2023). A brain disorder characterized by episodes of abnormally increased neuronal discharge resulting in transient episodes of sensory or motor neurological dysfunction, or psychic dysfunction. "Eight patients from four families were described in a first report, with encephalopathy, epilepsy, and progressive choreoathetosis, harboring biallelic pathogenic loss-of-function variants in the FRRS1L gene." (PMID 36835207, 2023). "Studies in patients have found nine families with recessive mutations in FRRS1L, which result in severe intellectual disability, movement disorders, hypotonia and epilepsy." (PMID 30692144, 2019). "Indeed, loss-of-function mutations of FRRS1L in human lead to epilepsy, prominent choreoathetosis, and severe impairment of cognitive functions." (PMID 29276473, 2017). "Recent proteomic studies have identified that Ferric Chelate Reductase 1 Like protein (FRRS1L), whose mutations in human lead to epilepsy, choreoathetosis, and cognitive deficits, is present in native AMPAR complexes in the brain." (PMID 29276473, 2017). "DNAJC5, FRRS1L, SHANK3, SYN1, and SYN2 were epilepsy-related genes." (PMID 33584793, 2020).
Intellectual disability (5 papers, 2017 to 2025). "Defective biogenesis by different mutations of FRRS1l underlies severe intellectual disability in humans." (PMID 28675162, 2017). "Bi-allelic mutations in the human FRRS1L gene are shown to cause severe intellectual disability with cognitive impairment, speech delay and epileptic activity." (PMID 28675162, 2017). "This co-assembly with the AMPAR pore and/or the stability of the FRRS1l protein is largely affected by the mutations identified in patients with intellectual disability." (PMID 28675162, 2017). "Additionally, the AMPAR complex-interacting Frrs1l protein was shown to cause severe intellectual disability with cognitive impairment, speech delay, and epileptic activity." (PMID 38891076, 2024). "Mutations in FRRS1l are associated with intellectual disability and epilepsy in three families." (PMID 28675162, 2017). "Finally, we investigated the mutations identified in patients with intellectual disability for their impact on protein expression and assembly of FRRS1l." (PMID 28675162, 2017).
cognitive deficits (4 papers, 2017 to 2024). "Loss-of-function mutations in a human AMPA receptor-associated protein, ferric chelate reductase 1-like (FRRS1L), are associated with a devastating neurological condition incorporating choreoathetosis, cognitive deficits and epileptic encephalopathies." (PMID 30692144, 2019).
Encephalopathy (4 papers, 2019 to 2024). Encephalopathy is a term that means brain disease, damage, or malfunction. "Ferric chelate reductase 1 like (FRRS1L) encephalopathy is a rare cause of DEE with only a few cases reported worldwide and with mostly drug-refractory seizures." (PMID 35250833, 2022). "The CSWS EEG pattern has also been found in ferric chelate reductase 1-like (FRRS1L) encephalopathy." (PMID 38397281, 2024).
Epileptic encephalopathy (3 papers, 2017 to 2020). A condition in which epileptiform abnormalities are believed to contribute to the progressive disturbance in cerebral function. "FRRS1L is related to epileptic encephalopathy, and its pathogenic variants have been reported previously." (PMID 33584793, 2020). "Mutations in FRRS1L are associated with epileptic encephalopathy." (PMID 30692144, 2019).
Ataxia (2 papers, 2019 to 2022). Ataxia refers to impaired coordination of voluntary muscle movement. "The stargazin mouse has a mutation in TARP-2, an auxiliary subunit of AMPA receptors, which causes a general decrease in AMPA receptor function and phenotypes that overlap with Frrs1l mutants, specifically ataxia and impaired coordination." (PMID 30692144, 2019).
autosomal-recessive intellectual disability (1 paper, 2017). "Together with these latest reports, our results show that bi-allelic mutations in FRRS1L cause autosomal-recessive intellectual disability and suggest the importance of FRRS1l-containing AMPARs for normal brain development and function." (PMID 28675162, 2017).
Cerebellar atrophy (1 paper, 2019). Cerebellar atrophy is defined as a cerebellum with initially normal structures, in a posterior fossa with normal size, which displays enlarged fissures (interfolial spaces) in comparison to the foliae secondary to loss of tissue. "In some cases, several years after the onset of symptoms, human patients carrying mutations in FRRS1L express cerebellar atrophy and other pathological alterations in the brain." (PMID 30692144, 2019).
hyperkinetic disorder (1 paper, 2019). "Overall, this study determines, for the first time in vivo, how loss of FRRS1L function can affect glutamatergic signalling, and provides mechanistic insight into the development and progression of a human hyperkinetic disorder." (PMID 30692144, 2019).
FRRS1L also shares sentences with these, for which no sentence is quoted: Choreoathetosis (3 papers); Dyskinesia (2); schizophrenia (2); autism spectrum disorder (1); developmental delay (1); Dystonia (1); infantile epileptic encephalopathy (1); Learning disabilities (1); movement disorder (1); Myoclonus (1); Tremor (1); unspecified (1).